DSG1 (desmoglein 1)
Diseases named in the same sentence as DSG1 in open-access papers (continued):
Sharing a sentence is not in itself a finding about the gene and the disease.
pemphigus (continued). "Pemphigus refers to a group of rare autoimmune blistering diseases characterized by autoantibodies targeting desmosomal cadherins: most commonly desmoglein-1 (Dsg1) and desmoglein-3 (Dsg3)." (PMID 35755063, 2022). "In the so far largest multicenter prospective study, anti-Dsg1/ Dsg3 serum antibodies were, however, detected in 329 (98.5%) of 333 pemphigus sera diagnosed by the clinical picture and direct IF microscopy using widely available assays." (PMID 35755063, 2022). "The Dsg1/Dsg3 compensation theory explains why skin and mucosa are not equally affected by the target antigen specific autoantibodies in different pemphigus forms." (PMID 34447768, 2021). "Autoantibodies in pemphigus vegetans are against Dsg1 and Dsg3, as well as other proteins constituting the desmosome." (PMID 35187073, 2021). "For example, in pemphigus, anti-Dsg1 and anti-Dsg3 antibodies bind to keratinocyte adhesion proteins desmoglein-1 and -3, respectively." (PMID 34068035, 2021). "The majority of signalling molecules involved in pemphigus pathogenesis analysed so far including p38MAPK, PLC, and PKC were associated with both Dsg1 and Dsg3." (PMID 34434944, 2021). "In conclusion, anti-Dsg1 auto-antibody titers seem to be more useful for monitoring the extent of the disease and activity in pemphigus with mucocutaneous lesions." (PMID 32509225, 2020). "The authors showed that, in an endemic area of leishmaniasis and pemphigus in Brazil, IgG4 antibodies directed against Dsg1 of patients with pemphigus foliaceous recognize LJM11." (PMID 33108348, 2020). "Anti-Dsg-1 autoantibodies titers seem to be more useful in showing the extent of the disease and activity in pemphigus with mucocutaneous lesions." (PMID 32509225, 2020). "Cloning of the gene coding for the major pemphigus antigens, Dsg1 and Dsg3, has enabled the production of recombinant proteins, which are used to detect IgG autoantibodies by ELISA." (PMID 32642305, 2020). "Specifically, these targets are MEK1, TrkA, PI3Kα, and VEGFR2, as the corresponding inhibitors impaired anti‐Dsg1/3‐induced pathology in four different pemphigus model systems." (PMID 32815159, 2020). "Pemphigus foliaceus (PF) is an autoimmune bullous disease of the skin, characterized by the production of autoantibodies that recognize the desmosome protein desmoglein 1 (DSG1)." (PMID 31681304, 2019). "Anti-Dsg1 was detectable with a sensitivity of 19–52% (PV), 90% (PF), and 38% (mixed pemphigus panel) and a specificity of ≥99%." (PMID 31552014, 2019). "Commercial ELISA systems (MBL, Euroimmun) are available for the detection of autoantibodies against Dsg1 and Dsg3 in pemphigus and against envoplakin in paraneoplastic pemphigus." (PMID 31552014, 2019). "As expected, the vast majority of cultures resulted specific for Dsg1 and/or Dsg3, further confirming the major role of these antigens in pemphigus pathogenesis." (PMID 31275324, 2019). "Pemphigus foliaceus (PF) is one of the two major forms of pemphigus and it is characterized by blistering of the skin only and immunologically by circulating autoantibodies against desmoglein 1 (DSG1)." (PMID 31781120, 2019). "Depending on the subtype, pemphigus antibodies are mostly directed against desmoglein 3 (Dsg3) and desmoglein 1 (Dsg1)." (PMID 31749790, 2019). "In contrast to Dsg1, pemphigus autoantibodies against Dsg3 directly interfere with Dsg interaction, which alone is not sufficient to cause loss of keratinocyte adhesion." (PMID 31178865, 2019). "One potential limitation of Dsg3 CAAR-T-cell therapy in pemphigus IgG-driven autoimmunity not only against Dsg3 but also against Dsg1." (PMID 31293582, 2019). "Dsg1-dependent suppression of EGFR/ERK signaling pathway has been shown to promote epidermal differentiation linking this signaling pathway to pemphigus autoantigens." (PMID 31867019, 2019).
pemphigus (continued). "Pemphigus foliaceus (PF) is one of the two main forms of pemphigus and is characterized by circulating IgG to the desmosomal cadherin desmoglein 1 (DSG1) and by subcorneal blistering of the skin." (PMID 31781120, 2019). "Mabs specific for the cytoplasmic precursor form of Dsg1 (preDsg1) have been cloned from pemphigus patients and from healthy individuals." (PMID 31275324, 2019). "We focused on ERK because it was observed previously that this pathway is activated only when antibodies against Dsg1, which are known to be primarily important for epidermal blistering in pemphigus, were present in autoantibody fractions." (PMID 31057535, 2019). "Taken together, the data presented demonstrate that keratins differentially regulate the binding properties of Dsg1 and 3, the two major antigens of pemphigus." (PMID 29616033, 2018). "Binding of pemphigus autoantibodies to the extracellular domains of Dsg1 and 3 on the surface of living keratinocytes was shown to induce altered clustering of the targeted molecules." (PMID 29643851, 2018). "This is in line with an altered clustering of Dsg1 in pemphigus patients’ lesions which was described using electron microscopy." (PMID 29616033, 2018). "Two representative classical IgG types of pemphigus are pemphigus vulgaris (PV) and pemphigus foliaceus (PF), which react with desmoglein 3 (Dsg3) and Dsg1, respectively, although there are many other forms of pemphigus." (PMID 29867971, 2018). "Pemphigus is a rare life-threatening autoimmune bullous disease, in which the anti-Dsg-1 and anti-Dsg-3 autoantibodies mediate the humoral immune response, causing deep erosions and blisters." (PMID 30083474, 2018). "The serological diagnosis of pemphigus relies on the demonstration of circulating anti-Dsg1 and anti-Dsg3 by ELISA and/or by indirect immunofluorescence (IIF) on monkey esophagus substrate." (PMID 29740444, 2018). "In pemphigus, autoantibodies target desmoglein 1 (Dsg 1) and Dsg 3, which play a major role in desmosomes essential for cell–cell adhesion between keratinocytes and cause blister formation with acantholysis." (PMID 30228865, 2018). "It is inconsistent with other studies, which demonstrated that decrease in anti-Dsg-1 antibody and anti-Dsg-3 antibody level is parallel with the clinical improvement in pemphigus patients." (PMID 30083474, 2018). "A few reports in literature describe the existence of antibodies against Dsg1 and/or Dsg3 in patients affected by skin conditions other than pemphigus especially patients affected by lichen planus." (PMID 29740444, 2018). "In fact, in a large prospective study with more than 330 pemphigus patients, only 4% of all pemphigus sera and 2.7% of PV and PF sera exhibited anti-desmocollin reactivity, while 98% of sera contained anti-Dsg3 and/or anti-Dsg1 IgG." (PMID 30233569, 2018). "There are two major subtypes of pemphigus: pemphigus vulgaris (PV), which is characterized by autoantibodies to Dsg3, and pemphigus foliaceus (PF), characterized by autoantibodies to Dsg1." (PMID 28184292, 2017). "In pemphigus foliaceus (PF), typically only anti-DSG1 autoAb, superficial blistering and erosions are observed." (PMID 28928733, 2017). "Along the same lines, a correlation between increased levels of anti-Dsg1 autoantibodies and a higher disease activity has previously been reported in patients with pemphigus." (PMID 25896794, 2015). "Autoreactive Th2 cell responses directed against the extracellular domain of desmoglein 1 and 3 have been conclusively documented in pemphigus patients." (PMID 24160488, 2014). "Since inhibition of RhoA has been shown to be induced by pemphigus autoantibodies that disrupt Dsg3 and Dsg1 adhesion we also performed RhoA pull down in parallel using the GST fused Rhotekin-PBD." (PMID 22796473, 2012). "Inhibition of Rac1 and RhoA by pemphigus autoantibodies targeting Dsg3 and Dsg1 showed disruption of cell–cell adhesion and blister formation in epidermis." (PMID 22796473, 2012).
pemphigus (continued). "It is a superficial formof pemphigus, with acantholysis in the granular layer of epidermis due to the circulation of autoantibodies toa 160–kDa intercellular antigen (desmoglein 1), in the desmosomes of keratinocytes." (PMID 20302202, 2010). "The recent availability of cDNA clones for pemphigus antigens has allowed the production of recombinant desmoglein 1 and desmoglein 3 molecules and the development of an ELISA approach in order to determine levels of antibodies to them." (PMID 20049340, 2009). "Transmembrane desmosomalproteins: desmoglein 1 (Dsg1) and desmoglein 3 (Dsg3) are pemphigus targetantigens." (PMID 18584045, 2008). "It is res iudicata in pemphigus pathologies that Dsg3 is the autoantigen of the vulgaris form, whereas Dsg1 is the autoantigen of the foliaceous form." (PMID 16925820, 2006). "Pemphigus foliaceus (PF) is a rare autoimmune blistering disorder characterized by superficial blistering of the skin due to autoantibodies targeting desmoglein 1 (Dsg1)." (PMID 40831828, 2025). "Notably, in the discrimination of pemphigus and BP, for Dsg1, Dsg3, and BP180 antibodies, the AUC values of CLIA were 0.95 (95%CI: 0.92~0.98), 0.84 (95%CI: 0.77~0.91), and 0.87 (95%CI: 0.82~0.93), which were the best among the three methods." (PMID 40661962, 2025). "Pemphigus is a rare group of autoimmune blistering disorders affecting the skin and mucous membranes, characterized by the formation of antibodies against cell surface adhesion molecules - specifically desmoglein 1 (Dsg1) and desmoglein 3 (Dsg3)." (PMID 40642697, 2025). "Concurrently, both anti-Dsg1 and anti-Dsg3 antibody levels, as well as blood methoxyephedrine, decreased, suggesting that rituximab, in combination with other agents, was an effective therapeutic option for treating pemphigus." (PMID 40135007, 2025). "Pemphigus disease area index (PDAI), IGC, IG%, C-reactive protein, neutrophil/lymphocyte ratios, platelet-to-lymphocyte ratio (PLR), anti-desmoglein 1, and anti-desmoglein 3 levels in patients with pemphigus were recorded retrospectively, and the statistical relationship between them was evaluated." (PMID 40068041, 2025). "In desmosomes, the pemphigus autoantigens desmoglein 1 (Dsg1) and Dsg3 link adjacent cells." (PMID 39882246, 2024). "Other target molecules of epidermal adhesion are now identified in the pathogenesis of pemphigus, as well as mitochondrial proteins, cholinergic receptors, and other molecules, which act synergistically with anti-Dsg1 and Dsg3 antibodies in epidermal acantholysis." (PMID 38851894, 2024). "Lab monitoring was often collected in pemphigus clinical trials, with anti‐desmoglein 1 and 3 levels being assessed in 28.3% of clinical trials, and immunoglobulins (IgG and/or IgM and IgA) (11.32%) and drug pharmacokinetics (9.4%) being frequently assessed as well." (PMID 39355721, 2024). "Furthermore, autoantibodies against DSG1 and DSG3 found in pemphigus cause loss of keratinocyte adhesion, indicating that loss of intercellular adhesion caused by autoantibodies from patients with desmosomal diseases is a hallmark of pathogenicity." (PMID 37450050, 2023). "As it has been shown that pathogenic antibodies targeting DSG1 and DSG3 lead to p38MAPK activation in pemphigus, we investigated whether this signaling pathway is activated by AC autoantibodies." (PMID 37450050, 2023). "It has been shown that antisera from pemphigus patients display different effects on signaling cascades, depending on the presence of Dsg1 antibodies, and these signaling responses could affect FcRn trafficking and degradation." (PMID 35326398, 2022). "Pemphigus is a chronic autoimmune skin blistering disease, characterized by acantholysis and by the production of autoantibodies directed against the structural desmosomal proteins desmoglein 1 (DSG1) and/or DSG3." (PMID 36452895, 2022). "In pemphigus patient skin, Dsg1 and Dsg3 immunostaining was altered especially along blister edges." (PMID 35711465, 2022).
pemphigus (continued). "We found that ADAM10 inhibition is protective against the pathogenic effects of pemphigus autoantibodies which primarily target Dsg3 but not Dsg1." (PMID 35844545, 2022). "The main characteristic of pemphigus is autoantibodies targeting Dsg1 and Dag3." (PMID 35449056, 2022). "Previous studies have shown that IgG and IgA antibodies in patients with IgG/IgA pemphigus could target Dsg1, Dsg3, and/or desmocollin 1 (Dsc1)–Dsc3 to a different extent, which may account for the mixed clinical presentations of the disease." (PMID 35625932, 2022). "However, AK23, which is a Dsg3-specific antibody from an active mouse model, and monoclonal autoantibodies targeting Dsg1 isolated from PF patients have been shown to induce pemphigus-typical acantholysis." (PMID 34434944, 2021). "Furthermore, recent studies have confirmed the existence of autoantibodies targeted at other non-Dsg1 and 3 antigens in pemphigus patients, providing the explanation for discrepancies and the evidence for the refutation of “desmoglein compensation theory”." (PMID 34829784, 2021). "In pemphigus in particular, the high efficacy of rituximab, the dramatic reduction of anti-Dsg1/anti-Dsg3 serum levels following rituximab, and the correlation of these autoantibodies with clinical response indicate that short-lived plasma cells are the main source of autoantibodies in this disease." (PMID 34068035, 2021). "Desmoglein 1 (Dsg 1) and desmoglein 3 (Dsg 3) are the primary target antigens in pemphigus." (PMID 34829784, 2021). "Studies on direct inhibition of Dsg1 and Dsg3 interaction in pemphigus." (PMID 34434944, 2021). "The hypothesis that the signalling pattern orchestrated by Dsg1 and Dsg3 in pemphigus are to some extent different also helps to explain why blister formation in pemphigus requires antibodies against Dsg1." (PMID 34434944, 2021). "Anti-Dsg1 and anti-Dsg3 antibodies are both well-studied markers for pemphigus." (PMID 33129291, 2020). "In pemphigus patients, CD19+ B cells and CD138+ PCs were found to be significantly increased in lesional skin and these isolated lymphocytes produced pathogenic anti-Dsg1 and anti-Dsg3 antibodies in vitro." (PMID 33297481, 2020). "In fact, besides Dsg3 and Dsg1, other non-desmoglein autoAbs, either pathogenic or non-pathogenic, have been identified in pemphigus patients." (PMID 31275324, 2019). "This may be related to the different mechanisms induced by autoantibodies against Dsg1 in pemphigus pathogenesis." (PMID 31024527, 2019). "In Australia, the process of diagnosing pemphigus involves typical physical findings, histopathology, direct immunofluorescence (DIF), indirect immunofluorescence (IIF), and enzyme-linked immunosorbent assay (ELISA) testing to Dsg1 and Dsg3." (PMID 29872685, 2018). "In the study presented here we show that keratins regulate the binding properties of Dsg1 and Dsg3, which are the major antigens in pemphigus, and propose a new concept how keratins could directly influence desmosomal adhesion." (PMID 29616033, 2018). "However, several IGAD cases showed clear acantholytic histology, suggesting that IgG antibodies to Dsg1 and/or Dsg3 induced the cell detachment similar to IgG-type pemphigus." (PMID 29867971, 2018). "In pemphigus, IgG1 antibodies against Dsg1 or 3 are present and they may also contribute to the blocking mechanism." (PMID 29483905, 2018). "Furthermore, SB202190 abolished PF-IgG-induced redistribution in wt cells indicating that p38MAPK signaling participates in the relocalization of Dsg1 from cell junctions in pemphigus." (PMID 29616033, 2018). "In a rare subset of pemphigus, known as pemphigus herpetiformis (PH), in which IgG autoantibodies targeting Dsg1 seems to be related to the development of disease, it was suggested that these autoantibodies were able to induce overexpression of IL-8 in keratinocytes." (PMID 28855908, 2017).
pemphigus (continued). "This hypothesis was confirmed by a transgenic mouse model in which increased Dsg2 levels limited superficial blister formation induced by the injection of pemphigus foliaceus (PF) antibodies targeting Dsg1 into neonatal mice." (PMID 23326495, 2013). "Pemphigus signifies a distinctive skin-specific acquired autoimmune disease characterized by intraepidermal blistering, which is induced by autoantibodies against desmosomal cadherins, desmoglein 1 (Dsg1), and Dsg3." (PMID 23936634, 2013). "In contrast, pemphigus foliaceus is characterized by antibodies directed against Dsg1." (PMID 23226536, 2012). "Pemphigus is a chronic mucocutaneous autoimmune bullous disease, characterized by the presence of autoantibodies against the desmosomal cadherins, desmoglein 1 (Dsg1), and/or desmoglein 3 (Dsg3)." (PMID 20585596, 2010). "Ultimately, utilization of questionnaires assessing disease severity, such as PDAI, in concert with lab monitoring of anti‐desmoglein 1 and 3 antibodies may best allow for a holistic evaluation of disease severity, progression, and outcomes in pemphigus clinical trials." (PMID 39355721, 2024). "In addition to Dsg3 and/or Dsg1 auto-abs, IgG auto-abs against several target proteins other than Dsgs such as desmocollin 3 were identified in pemphigus patients, raising speculations about potential synergic effects eventually triggering acantholysis." (PMID 37180099, 2023). "Therefore, it was proposed that Dsg1 and Dsg3 mediate autoantibody-specific signaling which may contribute to the different clinical phenotypes in pemphigus." (PMID 35634274, 2022). "Therefore, the adoptive transfer of anti-Dsg1 antibodies is sufficient to initiate pemphigus in adult mice, in which the pathogenicity of anti-Dsg1 autoantibodies can be studied in the process of disease onset and resolution and in the context of an intact immune system." (PMID 35920621, 2022). "Therefore, we speculated that ADAMs might also regulate adhesion of the pemphigus antigens Dsg1 and Dsg3." (PMID 35844545, 2022). "Further, a significant drop in autoantibody titers between pemphigus diagnosis and the first 12 months of follow-up occurred in the vast majority of patients with PV (83.6% and 87.1% for anti-Dsg1 and anti-Dsg3, respectively) and PF (94.4% and 83.3% for anti-Dsg1 and anti-Dsg3, respectively)." (PMID 35880183, 2022). "Furthermore, a higher co-localization of Dsg1 with Dsg3 in GL was observed for pemphigus patients." (PMID 35711465, 2022). "However, whilst it was shown that anti-Dsg1 and anti-Dsg3 antibodies are pathogenic, the role of most other antibodies for the pathology of pemphigus is not clear." (PMID 34434944, 2021). "In our study, anti-Dsg-1 antibody level was not positively associated with disease severity, which probably resulted from that most of the patients in our cohort were diagnosed as PV instead of other types of pemphigus." (PMID 30083474, 2018). "This CLIA showed strong agreement with IIFT-BIOCHIP, achieving area under the curve (AUC) values of 0.92 for anti-Dsg1/anti-Dsg3 and 0.84 for anti-BP180/anti-BP230 for differentiating pemphigus and BP." (PMID 40661962, 2025). "Our findings revealed good diagnostic value, with AUCs of 0.93 (95%CI: 0.89–0.98) for anti-Dsg1/anti-Dsg3 and 0.87 (95%CI: 0.82–0.92) for anti-BP180/anti-BP230 in differentiating pemphigus and BP, consistent with prior studies." (PMID 40661962, 2025). "This implies that periodic assessments of anti-Dsg1 IgG, anti-Dsg3 IgG, and DIF can predict relapse in pemphigus." (PMID 40084347, 2025). "A novel fully automated chemiluminescent immunoassay (CLIA) has been developed to quantify autoantibodies specific for desmogleins (Dsg1, Dsg3), BP180, and BP230, key target antigens in pemphigus and bullous pemphigoid." (PMID 40661962, 2025).